Y_RNA (Y RNA )
Gene: Miscellaneous RNA gene on chromosome 14 (50,468,397 to 50,468,498, reverse strand). Ensembl gene ENSG00000201573.
Homologues: Orthologues: macaque Y_RNA (87% identical). Paralogues in human: Y_RNA (84% identical), RNY1 (82% identical), Y_RNA (82% identical), RNY1P9 (81% identical), Y_RNA (81% identical), Y_RNA (80% identical), RNY1P5 (79% identical), Y_RNA (79% identical), Y_RNA (78% identical), RNY1P7 (77% identical), Y_RNA (77% identical), Y_RNA (76% identical), and 92 more.